RN7SL853P (RNA, 7SL, cytoplasmic 853, pseudogene)
Gene: Miscellaneous RNA gene on chromosome 15 (72,664,577 to 72,664,799, forward strand). Ensembl gene ENSG00000274350.
Homologues: Orthologues: macaque Metazoa_SRP (75% identical), macaque Metazoa_SRP (48% identical), macaque Metazoa_SRP (47% identical), macaque Metazoa_SRP (46% identical), macaque Metazoa_SRP (45% identical), macaque Metazoa_SRP (43% identical), macaque Metazoa_SRP (34% identical), macaque Metazoa_SRP (33% identical), macaque Metazoa_SRP (32% identical), macaque Metazoa_SRP (19% identical), macaque Metazoa_SRP (18% identical), macaque Metazoa_SRP (17% identical), and 2 more. Paralogues in human: RN7SL327P (100% identical), RN7SL429P (100% identical), RN7SL489P (100% identical), RN7SL241P (86% identical), RN7SL214P (83% identical), RN7SL417P (79% identical), RN7SL319P (78% identical), RN7SL469P (76% identical), RN7SL673P (76% identical), RN7SL495P (76% identical), RN7SL628P (76% identical), RN7SL719P (76% identical), and 709 more.